SNAI1 (snail family transcriptional repressor 1)
Diseases named in the same sentence as SNAI1 in open-access papers (continued):
Sharing a sentence is not in itself a finding about the gene and the disease.
tumor (continued). "This is also consistent with our PDX data where increasing expression of ZEB1/ZEB2/SNAI1 leads to lower tumor initiating capacity suggesting that a terminal mesenchymal phenotype has the lowest tumor initiating frequency." (PMID 29162812, 2017). "A recent study in epithelial cancer demonstrated cells that FBXO11 induced an increase of Snai1 and a decrease of E-cadherin to prevent tumor progression, thus characterizing FBXO11 as a tumor suppressor." (PMID 28403887, 2017). "A Boxplots showing the expression level of SNAI1 in microdissected normal epithelium, normal stroma, tumor epithelium and tumor stroma included in the ovarian profile GSE40595." (PMID 29041931, 2017). "It means that HOTAIR is involved in tumor metastasis of RCC partly through increasing the JMJD3-mediated SNAI1 upregulation." (PMID 28177890, 2017). "Specific silencing of Snai1 in human carcinoma cells leads to a dramatic reduction of in vivo tumor incidence and growth rate and increases the sensitivity to chemotherapeutics." (PMID 26985909, 2016). "Meanwhile, we analyzed the correlation with SNAI1 expression and clinical features of tumor progression and disease prognosis." (PMID 27239445, 2016). "Fortunately, our data showed that the knock down of SNAI1 can significantly diminish the tumor volume and weight and occasionally induce necrosis." (PMID 27239445, 2016). "The current understanding of the EMT process is that transcription factors including SNAI1, SNAI2, ZEB1, ZEB2 and TWIST1 down-regulate CDH1 expression which subsequently results in the loss of cell adhesion and migration of tumor cells." (PMID 26214683, 2015). "In these studies, CDH1 loss and overexpression of SNAI1, TWIST1 and LAMC2 were observed at the invasive front of the tumors, particularly in single or cords of tumor cells detaching from the tumor mass." (PMID 26214683, 2015). "In support of this observation, reactivation of SNAI1 or SNAI2 has been associated with a high risk of metastasis and a poor prognosis in different tumor progression models, although an inverse correlation with E-cadherin expression is not always observed." (PMID 24638100, 2014). "SNAI1 is located on chromosome 20q13 that exhibits gene amplification in tumor samples from metastatic PCA." (PMID 24565133, 2014). "The targets of SNAI1 have been shown to be also involved in tumor development, immune repression and tumor recurrence." (PMID 24959930, 2014). "HIF-1α and SNAI1 expression was detected in 65% (43/66) and 59% (39/66) of tumor samples, respectively." (PMID 23496980, 2013). "In our work, SNAI1, due to its major role in tumor progression, is also selected to be the seed gene." (PMID 23894653, 2013). "The function of the Snai1 and Snai2 genes have been studied extensively during both vertebrate embryogenesis and tumor progression and metastasis, and play critically important roles during these processes." (PMID 23762348, 2013). "Many of the EMT-inducing transcription factors such as SNAI1 (SNAIL), SNAI2 (SLUG), ZEB1, ZEB2, TWIST1, FOXC2 and Goosecoid have been associated with tumor invasion and metastasis." (PMID 24040120, 2013). "Accordingly, expression of hallmark EMT genes such as Snai1/Snail1 and Fn1 was downregulated in the presence of a JNK inhibitor in conditions that increased expression of the Cdh1 gene in Amela tumor lines." (PMID 23173060, 2012). "Several studies have correlated SNAI1 expression with tumor growth and invasion, lymph node metastasis, effusion, distant metastasis, chemoresistance and the recurrence of tumors." (PMID 22276203, 2012). "Decreased expression of E-cadherin is a pivotal event in EMT, and in tumor cells it occurs through epigenetic silencing as well as through zinc finger transcriptional repressors such as SNAI1." (PMID 22276203, 2012). "Once in the nucleus, MUC1 acts as a co-activator for the expression of genes linked to tumor cell invasion and metastasis including the EMT-promoting genes TWIST1, SNAI1 and SNAI2." (PMID 22586492, 2012).
tumor (continued). "We observed that EGF induced nuclear localization of the MUC1 cytoplasmic domain leading to expression of genes linked to tumor cell invasion and metastasis including TWIST1, SNAI1 and SNAI2." (PMID 22586492, 2012). "It is triggered by a diverse set of stimuli e.g. growth-factor signaling, hypoxia and also by tumor-stromal cell interactions with transcription factors such as SNAI1, TWIST, SLUG and ZEB1." (PMID 21834956, 2011). "In a recent study of oral SCC a small group of cases with abundant SNAI1 expression in tumor cell nuclei had significantly shorter DSS." (PMID 21834956, 2011). "Expression of proteins that are characteristic of mesenchymal cells (e.g. vimentin, FSP1/S100A4, SNAI1, SNAI2, and stromelysin-3) and loss of epithelial markers (e.g. E-cadherin) correlates with tumor progression and poor prognosis." (PMID 21966391, 2011). "The SNAI1 and SNAI2 genes have been implicated in tumor progression and metastasis, and both were recently shown to be direct transcriptional target of ATF3 in human mammary cells." (PMID 21304988, 2011). "These rare SNAI1(+) cells were frequently seen either in the vicinity of inflammation or close to the invasion front of the tumor." (PMID 20181105, 2010). "SNAI1 expression in the tumor stroma was a frequent observation, raising further questions regarding the origin of these cells and the contribution of the stromal compartment to the malignant phenotype." (PMID 20181105, 2010). "We show here that SNAI1-associated EMT is present in OSCC and potentially contributes to tumor progression in at least a subset of tumors." (PMID 20181105, 2010). "SNAI1-positivity (nuclear, ≥ 5% tumor cells) was observed in 10 tumors and 5 metastases (n = 12 patients)." (PMID 20181105, 2010). "Slide review revealed a distinct, well circumscribed area within the primary tumor displaying E-cadherin(-), p63(-), SNAI1(+), FAK(+) phenotype." (PMID 20181105, 2010). "Two cases displayed a sarcomatoid component as part of the primary tumor with SNAI1(+)/FAK(+)/E-cadherin(-)/p63(-) phenotype, but disparate phenotypes in corresponding metastases." (PMID 20181105, 2010). "Taking into account the focal nature of tumor-associated EMT we used full sections of both primary tumors and metastases to explore SNAI1-associated EMT by immunohistochemistry." (PMID 20181105, 2010). "All 6 cases of the stromal category "SNAI1-abundant" had SNAI1 expression at a <5% level in the corresponding tumor area." (PMID 20181105, 2010). "The EMT can be triggered by the expression of various transcription factors, including the E-box binding factors Snai1 (snail) and Snai2 (slug), in response to soluble factors present in the tumor microenvironment, such as TGFβ." (PMID 19787069, 2009). "Both SNAI1 and PA system components play a major role in tumour migration and have been localised to the tumour leading edge." (PMID 19055748, 2008). "There is little data on Twist, Snai1 and Snai2 expression at the earliest steps of tumor progression." (PMID 21892299, 2008). "In particular, SNAI1 can bind to the promoter regions of ZEB1 and activate its transcription, contributing to the downregulation of E-cadherin and promoting the EMT process, which is associated with tumor progression and metastasis." (PMID 41481650, 2026). "We found that the levels of combination signatures CM-2 (HYAL-1 + N-Cadh) and CM-6 (HYAL-1 + N-Cadh + HAS-2 + SNAI1 + Slug + MMP-9) were elevated 5–8-fold in tumor specimens from patients who had or developed metastasis during follow-up compared to those who did not (p < 0.0001)." (PMID 40149256, 2025). "Conversely, exosomes derived from tumor-associated macrophages led to increased expression of TGF-β signaling pathway activators in meningioma cells, specifically TGFBI, SNAI1, MMP2, TGF-β1, TGF-β2, IGFBP7, and LTBP2, leading to tumor cells obtaining a more aggressive phenotype." (PMID 40486962, 2025).
tumor (continued). "Our experimental results revealed that the administration of T. pratense (400 mg/kg) in combination with DOX effectively reversed EMT in 4T1 tumor cells, indicating that isoflavonoids may modulate Snai1 expression by inhibiting NF-κB." (PMID 40969409, 2025). "A study exploring the neuroendocrine characteristics of NB targeted the delta-like ligand 3 (DLL3), an inhibitory Notch ligand selectively upregulated in neuroendocrine tumors where it potentiates tumor proliferation and invasion by activating the Notch and the SNAI1/Snail signaling pathways." (PMID 40129921, 2025). "As a key regulator of EMT, SNAI1 plays a significant role in tumor invasion and metastasis." (PMID 39538371, 2024). "Furthermore, our findings demonstrated that SNAI1 regulates macrophage polarization and thus stimulates tumor stemness." (PMID 39702326, 2024). "SNAI1 is a classic TF that modulates EMT in various tumor types." (PMID 39722890, 2024). "CYD19 compound weakens tumor invasion and metastasis by reversing SNAI1-driven EMT, which suggests that pharmacological interference on SNAI1 epigenetic modification may take effect in patients." (PMID 39538371, 2024). "Although the beneficial effect of reduced endothelial Snai1 expression on supply, metastasis, and drug response was evident in all tumor models, we also observed differences, especially in the effect on primary tumor growth." (PMID 39095583, 2024). "Repression of endothelial Snai1-expression in the strongly pro-angiogenic tumor microenvironment has the opposite effect, reducing the ill-fated excessive sprouting via increased Notch1/Dll4 expression, leading to stable vessels that are no longer prone to constant remodeling and degradation." (PMID 39095583, 2024). "SNAI1 knockdown using siRNA delivered by nanoparticles in orthotopic patient-derived xenografts, resulted in decreased stemness, higher let-7 expression, and lower tumor burden in vivo." (PMID 38836981, 2024). "Expectedly, TGFβ caused a massive upregulation of SNAIL (encoded by the SNAI1 gene), one of several transcription factors that are critically involved in the acquisition of a mesenchymal phenotype by epithelial tumor cells." (PMID 39482615, 2024). "Our findings indicate that changes in ZEB1 and SNAI1 expression in PCa are associated with the induction of DEGs and downstream pathways that influence the TME and may facilitate immune evasion during tumor progression." (PMID 38672562, 2024). "This may be mediated by the activation of some invasion-related MAP kinases (such as AKT, ERK, JNK, or p38) and supplemented by increasing the amount of SNAI1 clusters in the tumor cell nucleus." (PMID 39767739, 2024). "Besides, SNAI1 is assumed as one of the most important factors concerning tumor invasiveness, while the down-regulation of ZEB-1 and TWIST is associated with tumor progression and poor prognosis." (PMID 39538371, 2024). "An increase in SNAI1 expression was observed to correlate with tumor progression and recurrence." (PMID 39273022, 2024). "Conversely, Snai1 silencing effectively suppresses tumor growth and invasiveness." (PMID 37190245, 2023). "Conclusively, these results deduced that the aberration of the GATA6-AS1/SNAI1 axis may be responsible for tumor progression and EMT process in PDAC cells under normoxic as well as hypoxic conditions." (PMID 38057853, 2023). "Furthermore, ectopic expression of SNAI1 partially rescued the GATA6-AS1 overexpression-repressed tumor burden and tumor proliferation." (PMID 38057853, 2023). "TWIST2 and SNAI1 are key regulators of tumor epithelial mesenchymalization." (PMID 37091977, 2023). "Furthermore, miR-153 overexpression suppressed tumor cell proliferation and invasion but motivate cell apoptosis by targeting snail family transcriptional repressor 1 (SNAI1)." (PMID 37124518, 2023). "Studies have demonstrated that SNAI1 is a tumor-promoting factor." (PMID 35898399, 2022).
tumor (continued). "For example, EZH2 could promote tumor progression by interacting with SNAI1 and being driven to the promoter of E-cadherin, thus suppressing gene expression." (PMID 35597793, 2022). "For example, the overexpression of Gli1, a key protein in the Hh pathway, is considered as a symbol of Hh pathway activation and is able to activate oncogene target genes such as Cyclin-D1, Myc, Bcl-2, Ang1/2, Snai1, Nanog, and Sox2 to promote carcinogenesis and tumour development." (PMID 36358596, 2022). "To determine whether FTO plays an anti-tumour role by inhibiting the expression of SNAI1 in EOC, we first established A2780 and OVCAR3 cell lines stably transfected with anti-FTO shRNA (sh-FTO) lentivirus." (PMID 36358640, 2022). "It has been proved that AKAP1, SNAI1 and Caprin1 could be target genes of miR-199a-5p, and their overexpression worsens tumor developments." (PMID 35517408, 2022). "SNAI1/2 are related to the malignant biological properties of tumor cells." (PMID 35898399, 2022). "For instance, the overexpression of SNAI1 in tumour cell lines promotes tumour metastasis." (PMID 35259952, 2022). "Aberrant AURKA expression/activity is required to promote tumor progression because of its central role in mediating TGF-β-induced SNAI1 gene expression, cancer cell plasticity, and the enrichment of ALDH1high cells harboring high self-renewal capacity and intrinsic chemoresistance." (PMID 33674749, 2021). "Furthermore, a direct association between stromal SNAI1 expression and that of the endothelial marker CD34 was observed in tumor specimens from CRC patients." (PMID 34768901, 2021). "Furthermore, tumor let-7 levels increased 2–3 fold, consistent with SNAI1-mediated repression of let-7 in vivo." (PMID 33806868, 2021). "In orthotopic PDX, SNAI1 knockdown results in increased let-7 levels and reduced tumor growth." (PMID 33806868, 2021). "We present evidence that the RNase activity of MCPIP1 might mediate tumor progression by controlling the transcriptional activation of β-catenin; promoting the expression of the transcription factors SNAI1, SNAI2, TWIST, and ZEB1; and inducing EMT." (PMID 34657130, 2021). "In this study, we hypothesized that SNAI1 directly represses miRNA let-7 transcription, and that SNAI1 knockdown would result in restoration of let-7 expression and reduction of stemness and tumor growth." (PMID 33806868, 2021). "Furthermore, FBXO45 modulated the process of EMT via mediating the ubiquitination and degradation of substantial EMT-related transcription factors, such as Twist1, Snai1/2, and Zeb1/2, in tumor cells." (PMID 35046938, 2021). "Therefore, SNAI1 accelerates the progression of the disease and increases the infiltration of neutrophils in the tumor to maintain the harmful tumor microenvironment." (PMID 32833672, 2020). "In addition, TTP has been shown to be able to revert mesenchymal to epithelial phenotype in many tumor cell lines, by down regulating the transcriptional repressors SNAI1 and TWIST1." (PMID 32784485, 2020). "Moreover, we detected the relationship of SNAI1 and tumor-infiltrating immune cells in gastrointestinal cancers." (PMID 32833672, 2020). "In certain tumor cells, SNAI1 upregulates ZEB1 and ZEB2 expression." (PMID 32226439, 2020). "The Snai1 transcriptionally represses E-cadherin and promotes tumor proliferation and invasion." (PMID 32071290, 2020). "Moreover, other studies have suggested that autophagy attenuates EMT and tumor metastasis by the degradation of Twist1 and SNAI1." (PMID 30736337, 2019).
tumor (continued). "Importantly, a single-ApoSQ injection leads to the enhanced induction of PPARγ and PTEN mRNA and protein expression and to a reciprocal reduction in phosphorylated Akt, as well as in the mRNA levels of Snai1 and Zeb1, within primary tumor tissue." (PMID 30842627, 2019). "Interestingly, the enhancement of PTEN and CD36 and the reduction in Snai1 and Zeb1 mRNA expression in the tumor tissue by ApoSQ injection were reversed by GW9662 treatment." (PMID 30842627, 2019). "Snail1 plays an important role in epithelial to mesenchymal transition (EMT) during tumor metastasis; however, whether Snai1 potentiates the process of neoangiogenesis is completely unknown." (PMID 30975732, 2019). "Indeed, miR-199-5p represses SNAI1 by binding to the mRNA’s 3’ untranslated region, and SNAI1 knockdown reduces cell invasion and tumor growth in xenotransplants." (PMID 31482959, 2019). "In fact western blot analysis of proteins extracted from A375M/SCD5 tumor nodules, in addition to Snail Family Transcriptional Repressor 1 (SNAI1/SNAIL) and Twist Family BHLH Transcription Factor (TWIST) reduction and ZEB2 up-regulation, showed the induction of E-cadherin." (PMID 29484133, 2018). "On comparing PBMC expression profiles with patient disease characteristics, SNAI1 expression in PBMCs indicated a significant decrease in cases harboring large tumor sizes T2 (p = 0.036), T3 (p = 0.008) and T4 (p = 0.041) in comparison to patients presented with smaller tumor size T1." (PMID 28607365, 2017). "The targets of SNAI1 have been shown to be involved in tumor development and tumor recurrence." (PMID 28424413, 2017). "Taken together, these data indicate that a higher expression of SNAI1 may accelerate tumor invasion and metastasis, functions that may be correlated with a poor prognosis." (PMID 27239445, 2016). "In addition, patients with incomplete tumor capsule formation had higher levels of SNAI1 expression than patients with complete tumor capsule formation." (PMID 27239445, 2016). "CDH1 transcriptional repressors, such as SNAI1 (SNAIL), SNAI2 (SLUG), ZEB1, ZEB2 (SIP1), E12/E47, and TWIST have traditionally been implicated in promoting EMT in various systems of embryonic development and tumor progression." (PMID 24968068, 2014). "However, we also identified and confirmed the upregulation of SNAI1, which promotes tumour growth and metastasis in various solid tumours, including ovarian." (PMID 22166800, 2012). "Importantly, following EGF treatment, we detected elevated transcript levels of several MUC1 target genes linked to tumor cell invasion including TWIST, SNAI1, and SNAI2." (PMID 22586492, 2012). "Moreover, in all samples of IDC with decreased PKD activity a correlating decrease in SNAI1 phosphorylation at S11 in the nucleus of tumor cells was detected, whereas total SNAI1 levels were comparable in all samples including normal ductal epithelium." (PMID 22276203, 2012). "The EGFR mutated SNAI1 reactivated tumor express TWIST1, VIM and CDH2 (sample 288) suggesting that TWIST1 and SNAI1 might interact to drive full mesenchymal phenotype." (PMID 22272264, 2012). "Individual SNAI1(+) tumor cells were seen in primary tumors of 30 patients." (PMID 20181105, 2010). "The primary tumor in this case presented as exophytic mass with a minor component of distinctly squamous cell nests and a major, poorly differentiated component with E-cadherin(-), p63(-), SNAI1(+), FAK(+) phenotype." (PMID 20181105, 2010). "However, SNAI1 expression in tumor cells was an infrequent event in the majority of cases (usually <<5%) and more commonly noted in scattered individual cells or small groups, particularly at the invasion front and in the vicinity of inflammation." (PMID 20181105, 2010). "Next, we studied SNAI1 expression in tumor cells with regard to patient prognosis." (PMID 20181105, 2010).